IL6 (interleukin 6)
Diseases named in the same sentence as IL6 in open-access papers (continued):
Sharing a sentence is not in itself a finding about the gene and the disease.
Insulin resistance (continued). "Notably, other cytokines, such as TNF-α and IL-6, known for their important role in insulin resistance, were not detectable in most enrolled subjects, so could not be included in the analysis." (PMID 37628530, 2023). "However, it is not clear whether the increased levels of IL-6 can be attributed to insulin resistance that too on an acute basis." (PMID 35986233, 2022). "Although the overall effect of vitamin E supplementation on serum concentrations of interleukin-6 (IL-6) was not significant, a significant reduction in this cytokine was seen in studies that used α-tocopherol and those trials that included patients with disorders related to insulin resistance." (PMID 33057114, 2020). "Also, they could improve the composition of gut microbiota and intestinal integrity as well as suppress the production of proinflammatory mediators such as interleukin-6 (IL-6) and tumor necrosis factor-α (TNF-α), and therefore may reduce inflammation, oxidative stress and insulin resistance." (PMID 31827628, 2019). "Therefore, the fourth limitation is that we did not measure other cytokines, such as leptin, adiponectin, IL-6 and TNF-α, which may be related to serum irisin level and may confound the association between irisin and insulin resistance." (PMID 27473122, 2016). "However, possibly due to the prevailing inflammation, in obese individuals IL–6 may have negative effects and precipitate insulin resistance." (PMID 26448147, 2015). "However, the data concerning regulation of the whole-body glucose and lipid metabolism in IL-6−/− animals are not so evident since one group referred to age-related insulin resistance and weight gain of IL-6−/− mice while the other did not confirm this observation." (PMID 24533077, 2014). "However, the role of IL-6 in the etiology of insulin resistance is not fully understood." (PMID 23762871, 2013). "Given that EPO treatment inhibits the NF-κB, ERK and JNK activation, and TNF-α and IL-6 production in animal models of hepatic injury, we hypothesize that EPO may also inhibit the HFD-induced chronic inflammation, contributing to the improvement of glucose intolerance and insulin resistance." (PMID 23326455, 2013). "Moreover, insulin resistance and increased adipose mass create an oxidative environment in the tissues that upregulates the expression of various pro-inflammatory cytokines, including tumor necrosis factor-α (TNF-α) and interleukin-6 (IL-6), which stimulate tumor growth and progression." (PMID 22312273, 2012). "Indeed, a recent study demonstrated that mice lacking IL-6 were prone to develop hepatosteatosis, liver inflammation and insulin resistance when compared to wild-type mice, supporting a role for IL-6 in the suppression of inflammation and regulation of lipid homeostasis and metabolism in vivo." (PMID 21054880, 2010). "This study aims to address this critical research void by systematically examining IL-6 concentrations among PCOS patients, differentiating between individuals with and without insulin resistance." (PMID 40226143, 2025). "Compared to IL-6 and TNF-α, which indicate chronic inflammation, SHBG is a negative marker that is it decreases, worsening insulin resistance and hyperandrogenism." (PMID 40385768, 2025). "Visceral fat secretes pro-inflammatory cytokines (IL-6, TNF-α), promoting systemic inflammation and insulin resistance, which can lower HDL and raise non-HDL cholesterol, increasing cardiovascular risk." (PMID 40632711, 2025). "Although blocking the trans-signaling pathway of IL-6 improves ATM accumulation induced by a high-fat diet, it does not alleviate systemic insulin resistance." (PMID 39749325, 2024). "Moreover, the selective blockade of IL-6 trans-signaling (and not IL-6R) prevents AT macrophage accumulation in HFD-induced obese mouse models without exacerbating insulin resistance, suggesting that targeting IL-6 trans signaling could also be a more favorable option for inflammatory diseases." (PMID 35909571, 2022).
Insulin resistance (continued). "In response to voluntary physical activity, endogenous IL‐6 plays an important role in preventing insulin resistance under a HFD, and this beneficial metabolic effect is absent in IL‐6 KO mice." (PMID 33650753, 2021). "Subjects with insulin resistance had a higher concentration of hs-CRP (p = 0.002) and IL-6 (p = 0.002) than subjects without insulin resistance." (PMID 29466985, 2018). "The patients classified as being insulin-resistant had higher inflammatory markers (CRP, TNF-alpha, and IL-6) and higher disease activity: mean DAS28 score in the non-IR group was 3.6, and in the IR group it was 4.6." (PMID 28932748, 2017). "In this study, CRP, IL-6, and TNF-α were significantly elevated in obese Egyptian type 2 diabetics and positively correlated with insulin resistance, non-HDL and triglycerides, key components of metabolic syndrome." (PMID 29099041, 2017). "In conclusion, in this study, CRP, IL-6, and TNF-α were significantly elevated in obese Egyptian type 2 diabetics and were positively correlated with insulin resistance, non-HDL and triglycerides." (PMID 29099041, 2017). "The change of serum interleukin-6(IL-6) levels in women with polycystic ovary syndrome (PCOS), as well as the relations between IL-6 levels and body mass index (BMI), insulin resistance(IR) and androgen status of PCOS patients, are not fully understood." (PMID 26849353, 2016). "In addition to adipocyte-derived factors, increased release of TNF-α, IL-6, monocyte chemo-attractant protein-1 (MCP-1) and additional products of macrophages and other cells that present in adipose tissue might also have a role in the development of insulin resistance." (PMID 25781947, 2015). "However, unlike IL-6, TNF-α can only increase insulin resistance by inhibiting AMPK signaling pathway and decreasing glucose uptake, impairing insulin signaling and lipid metabolism." (PMID 41515940, 2025). "Since our study did not evaluate inflammatory markers/cytokines, such as IL-6, oxidized LDL, small dense LDL, or insulin resistance, it was difficult to elucidate the mechanism by which CHIP interacts with LDL cholesterol to increase the risk of type 2 diabetes." (PMID 37457265, 2023). "Besides, insulin levels, insulin resistance (HOMA-IR) and inflammatory markers (such as: CRP and IL-6) were not complete for all patients." (PMID 35193565, 2022). "Furthermore, Metrnl illustrated a negative correlation with IL-6 and TNF-α in both CAD patients and also with BMI, insulin resistance, IL-6 and TNF-α in T2DM patients." (PMID 30212581, 2018). "Visceral adiposity has been complicated with negative effects including insulin resistance and the elevated production of pro-inflammatory molecules leptin (LEP), resistin, tumor necrosis factor-α (TNF-α), IL-6, hypoxia-inducible factor 1 (HIF-1) and adipocyte fatty-acid binding protein (A-FABP)." (PMID 27703473, 2016). "Therefore, hypothetically it is possible that TNF-α actually induces impaired glucose metabolism, while high systemic levels of IL-6 reflect a high local production of TNF-α and are not directly involved in the pathogenesis of insulin resistance." (PMID 22272193, 2012). "Nevertheless, the concentration of IL-6 and TNF-α showed a non-significant trend to increased values in the O group compared to C. Vitamin E supplementation managed to reduce the concentration of both cytokines, which suggests that hepatic inflammation is not responsible for insulin resistance." (PMID 29028831, 2017). "However, due to the diverse pathological manifestations in different diseases, targeting only the IL-6 trans-signaling pathway in DKD may not be the most effective approach, as demonstrated by the inefficacy of sgp130Fc in ameliorating insulin resistance induced by a high-fat diet in mice." (PMID 39749325, 2024).
Insulin resistance (continued). "Furthermore, in the women with insulin resistance, intake of MOJ for 4 weeks reduced the plasma VCAM-1 levels (554.99 ± 15.63 to 545.31 ± 14.65 ng·mL−1, p = 0.039) but the plasma levels of ICAM-1, C-reactive protein, TNF-α, IL-6, and IL-10 were not significantly altered." (PMID 37469434, 2023).
depression (2,274 papers, 2006 to 2026). "In contrast, intracerebroventricular injection of MR16-1 did not yield antidepressant benefits in CSDS-susceptible mice, suggesting that peripheral IL-6 plays a key role in mediating depression-like behaviors in the CSDS model." (PMID 40028232, 2025). "In our study, we found that Fut8+/− mice had higher Il6 levels than the Fut8+/+ group, indicating that diminished core fucosylation predisposes mice to depression." (PMID 39864626, 2025). "Although CRP and IL-6 are well-established inflammatory markers that have been linked to depression in multiple studies, their specificity for depression is constrained by associations with various physical conditions." (PMID 40276074, 2025). "IL-6 can activate neutrophils and increase inflammation, is associated with depression and fatigue, alters sleep disturbances, and aggravates cognitive dysfunction." (PMID 40709232, 2025). "Inflammation plays a significant role in the overlap between sickness behavior and depression, as both are associated with elevated levels of pro-inflammatory cytokines, such as IL-1B, IL-6, and TNF-alpha." (PMID 40282388, 2025). "With the data available, significant associations between TNF-a, IFN-γ, IL-6 and IL-10 concentrations and level of depression were found suggesting that depression is associated with inflammatory responses in the immune system in individuals with MS." (PMID 39867847, 2025). "Higher levels of inflammatory markers, like interleukin-6 (IL-6) and C-reactive protein, are linked to depression." (PMID 40995176, 2025). "The literature highlighted an association between sleep deprivation or depression and high levels of specific cytokines, (IL-1, IL-6 and TNF-α)." (PMID 39852224, 2025). "In conclusion, the findings in this study suggest that high IL-6 associates with worse depression symptom trajectories observed at different stages of the life course, with stronger associations in younger individuals." (PMID 39865800, 2025). "Key gene–environment interactions, including those involving serotonin transporter (SLC6A4) and inflammatory genes (e.g., TNF-α, IL-6), have been implicated in depression." (PMID 40428308, 2025). "This suggests that at various points across the life course, higher IL-6 associates with worse depression symptom trajectories, with a relatively greater impact of IL-6 on depressive symptoms in younger compared to older people." (PMID 39865800, 2025). "Studies have shown that depression is linked to elevated levels of pro-inflammatory cytokines such as IL-6, TNF-α, and CRP." (PMID 40697716, 2025). "It was proposed that normalizing IL-6 activity is essential for treating depression linked to inflammation." (PMID 40001598, 2025). "In these replications, we confirmed that IL6 perturbation is associated with lower odds of depression (OR per 24% CRP decrease of 0.993, 95% CI 0.989 to 0.997, P = 0.002) and cholelithiasis or cholecystitis (OR of 0.896, 95% CI 0.803 to 0.999, P = 0.048)." (PMID 40858837, 2025). "This cytokine also activates the HPA axis, resulting in hypercortisolemia, a hallmark of chronic stress and depression, while our results showed that it reduced the levels of IL-6 in the brain." (PMID 40487411, 2025). "IL-6, often elevated in cancer patients with cachexia, has been correlated with weight loss, reduced food intake, and depression; high IL-6 plasma levels are associated with shorter survival in cachectic patients." (PMID 40572244, 2025). "Sex differences were also consistent in both cohorts but stronger in the younger cohort (ALSPAC), where the association between higher IL-6 and worse depression trajectories was stronger in females compared to males." (PMID 39865800, 2025). "IL-6, a cytokine induced by stress, is another molecule closely linked to the epigenetic mechanisms underlying depression." (PMID 41179817, 2025). "•Meta-analysis showed association between TNF-a, IFN-g, IL-6 and IL-10 and depression in individuals with MS." (PMID 39867847, 2025).
depression (continued). "Patients with major depressive disorder have elevated levels of IL-6 and deficient maturation of NK cells and T helper cells, suggesting that both cellular immunosuppression and increased cytokine production can occur in the same individual." (PMID 41356482, 2025). "Higher baseline IL-6 was associated with worse depression symptom trajectories in both cohorts (largest effect size: 0.046 [ALSPAC, age 16 years])." (PMID 39865800, 2025). "This process drives an imbalance between T helper 17 and regulatory T cells and elevates circulating levels of inflammatory cytokines such as IL-6, IL-1, and tumor necrosis factor, all of which are implicated in the pathogenesis of depression." (PMID 41409248, 2025). "Recent work has also highlighted a multi-protein-derived measure of IL-6 activity as a potential biomarker linked to clinical and cognitive outcomes in depression." (PMID 41450979, 2025). "Mendelian randomization analyses provide additional evidence by demonstrating a causal link between genetically predicted elevations in inflammatory biomarkers—such as CRP and IL-6—and increased susceptibility to depression." (PMID 40510937, 2025). "For instance, increased concentrations of peripheral biomarkers of inflammation, such as C-reactive protein (CRP) and interleukin-6 (IL-6), are associated with future symptoms of depression, and decrease with antidepressant treatment." (PMID 40494639, 2025). "IL-17 A-induced inflammatory mediators, including IL-6, IL-1β, Ptgs2, Csf2, and Cxcl1, can cause myocardial inflammation and depression [,14], and have been associated with endotoxin-induced cardiac dysfunction and shock [14,]." (PMID 41311862, 2025). "Our previous study found that IL-6 was associated with the total number of depressive episodes, representing increased burden of depression in ALSPAC." (PMID 39865800, 2025). "The association between TNF-α and IL-6 and the Beck and Hamilton depression scales was analyzed in a group of 116 RA patients with depression." (PMID 40699818, 2025). "Individuals with depression often exhibit elevated levels of inflammatory markers including IL-1β, IL-6, TNF-α, and CRP, which are directly associated with acute cardiovascular events." (PMID 41179812, 2025). "Although effect sizes were small, higher levels of TNF-α, IL-1β, IL-6, and IL-8 were all linked to either more depressive symptoms and/or greater odds of meeting criteria for clinical depression." (PMID 39902492, 2025). "Improvements in circulating BDNF, kynurenine, and IL-6 levels were associated with reductions in depression symptoms." (PMID 40665827, 2025). "Peripheral inflammatory markers, including serum interleukin 6 (IL-6), are associated with depression, but less is known about how these markers associate with depression at different stages of the life course." (PMID 39865800, 2025). "Positive associations between CRP and interleukin-6 (IL-6; a proinflammatory cytokine), and somatic depression symptoms have been observed in adults and children." (PMID 40823322, 2025). "IL-6 has been implicated in depression and fatigue with evidence that increased IL-6 concentrations have been linked to depressive symptoms and increased circulating IL-6 linking to fatigue." (PMID 41050477, 2025). "These associations were stronger in the younger ALSPAC cohort, where additionally higher IL-6 levels at age 9 years was associated with worse depression symptoms trajectories in females compared to males." (PMID 39865800, 2025). "Depression exhibits close associations with elevated systemic inflammatory cytokines including interleukin-6 (IL-6), IL-1β, tumor necrosis factor-α (TNF-α), and C-reactive protein (CRP)." (PMID 40508038, 2025). "Second, although CRP is commonly used to index overall inflammation, has been associated with depression, and is related to other inflammatory markers including IL-6, it is still a single inflammatory marker." (PMID 40357904, 2025).